HEPFAL (hepatocellular carcinoma ferroptosis associative lncRNA)
Synonyms: KB-68A7.1; formerly LINC03038
Gene: Long non-coding RNA gene on chromosome 21 (44,475,723 to 44,478,493, forward strand). Ensembl gene ENSG00000274225.
Diseases named in the same sentence as HEPFAL in open-access papers:
HEPFAL is named in the same sentence as 4 diseases in open-access papers, as found by Europe PMC text mining. Sharing a sentence is not in itself a finding about the gene and the disease. The quoted sentences say what the papers report.
hepatocellular carcinoma (5 papers, 2022 to 2025). A malignant tumor that arises from hepatocytes. "It has been reported that lncRNA HEPFAL accelerates ferroptosis in hepatocellular carcinoma by regulating SLC7A11 ubiquitination." (PMID 39194582, 2024). "Another study indicated that lncRNA HEPFAL contributes to ferroptosis in hepatoma cells by facilitating the ubiquitination of SLC7A11." (PMID 39267831, 2024). "Furthermore, lncRNA HEPFAL promotes the ubiquitination of SLC7A11, reducing its stability and inducing ferroptosis in hepatocellular carcinoma cells." (PMID 40191204, 2025). "Additionally, lncRNA HEPFAL can promote the ubiquitination of SLC7A11, reducing its stability and inducing ferroptosis in hepatocellular carcinoma cells, which can also impact the function of macrophages in the tumor microenvironment." (PMID 40191204, 2025).
liver cancer (1 paper, 2022). An epithelial or non-epithelial malignant neoplasm that arises from the liver. "To verify the regulation of lncRNA HEPFAL on SLC7A11, we detected the expression levels of lncRNA HEPFAL and SLC7A11 in liver cancer cell lines." (PMID 36008384, 2022). "This study reported that lncRNA HEPFAL, upstream of the key ferroptosis gene SLC7A11, regulates ferroptosis in liver cancer cells." (PMID 36008384, 2022).
tumor (3 papers, 2021 to 2024). "The results showed that the mice in the control group and the HEPFAL overexpression group both had therapeutic effects on the tumor." (PMID 36008384, 2022). "The tumor volume and weight of the HEPFAL overexpression group were significantly reduced." (PMID 36008384, 2022). "However, the tumor treatment effect of the group of HEPFAL overexpression was more significant, which also verified our previous in vivo experiments that HEPFAL can increase the sensitivity of erastin-induced ferroptosis." (PMID 36008384, 2022). "In addition, we found that the expression level of SLC7A11 in the overexpressing HEPFAL group was lower than that of the control group, and the number of tumor cells in the overexpression HEPFAL group was the lowest." (PMID 36008384, 2022). "Through K–M analysis of HCC patients in TCGA, we found that the OS of patients with high expression of lncRNA HEPAL was longer than that of patients with low expression, which was consistent with the expression trend of lncRNA HEPFAL in tumor and normal tissues." (PMID 36008384, 2022). "To further clarify the role of lncRNA HEPFAL and SLC7A11 in HCC, we collected tumor and normal tissue samples from 60 HCC patients at WMU hospital." (PMID 36008384, 2022). "We found that the expression of lncRNA HEPFAL in tumor tissues was significantly lower than that in normal tissues, while SLC7A11 expression was higher in tumor tissues." (PMID 36008384, 2022).
cancer (1 paper, 2022). A tumor composed of atypical neoplastic, often pleomorphic cells that invade other tissues. "Therefore, we collected 60 patient samples with cancer and normal tissues and found that the expression of lncRNA HEPFAL in HCC tissues was lower than that in normal liver tissues, which was in line with the trend in the TCGA database." (PMID 36008384, 2022).